IL1B (interleukin 1 beta)
Diseases named in the same sentence as IL1B in open-access papers (continued):
Sharing a sentence is not in itself a finding about the gene and the disease.
COVID-19 (continued). "Our data supports that the uptake of cell corpses infected with SARS-CoV-2 exacerbates the secretion of inflammatory IL-6 and IL-1β, suggesting a mechanism for the robust secretion of cytokines related to COVID-19 cytokine storm." (PMID 35666101, 2022). "We focused our study on the key pro-inflammatory cytokines IL-6, TNF-α, IFN-γ and interleukins such as IL-1β because they were shown to be elevated in severe COVID-19 patients with severe disease." (PMID 35651623, 2022). "In the same way, canakinumab, a neutralizing mAb of IL-1β through competition for IL-1RI binding, is used to treat auto-inflammatory severe diseases and has been evaluated in COVID-19 patients." (PMID 35631442, 2022). "For the MGH cohort, comparable tertile groups were created according to TNF-α, IL-1β, IL-6 and IL-8 at admission for both mild and severe COVID-19." (PMID 35938070, 2022). "Recently, one study demonstrated that the TNF/IL1B–driven inflammatory response was dominant in COVID-19 across all types of cells among PBMCs using single-cell RNA sequencing." (PMID 36159873, 2022). "Recent research has discovered that elevated plasma levels of IL-1β and IL-6 expression are a typical sign of the cytokine storm generated by new coronavirus pneumonia (COVID-19)." (PMID 35669119, 2022). "The inhibition of TLR4 or IL-1β has therefore been proposed as a mechanism to alleviate COVID-19 symptoms." (PMID 35631059, 2022). "The first step in the COVID-19–related inflammatory cascade is IL-1β production that is initiated upon recognition of PAMPs and DAMPs by a multiprotein cytosolic complex called the inflammasome." (PMID 35495619, 2022). "Specialized pro-resolving mediators have been found to reduce the production of pro-inflammatory cytokines such as IL-6 and IL-1β, which are involved in the development of COVID-19." (PMID 36233111, 2022). "Patients with fatal COVID-19, in contrast to survivors, developed higher levels of mucosal spike-specific IgA than IgG but lost neutralizing activities over time and had reduced IL-1β in the lung." (PMID 36248831, 2022). "For example, severe COVID-19 was linked to changes in IL-13, IL6 and IL-1B, and multiple chemokines (e.g. CCL20, CCL27, CXCL10)." (PMID 36171541, 2022). "The levels of TNFa, IL-6, IL-1b, IFNg, IL-2, and IL-10 have been reported as inflammatory cytokines in COVID-19." (PMID 35669157, 2022). "In this research, we detected a significant content of IL-1β and IL-6 in the saliva of the V-COVID-19 group at the moment of the PCR diagnosis." (PMID 36497139, 2022). "In vitro studies have shown that caspase-1 is activated in patients with severe COVID-19, downstream secretion of IL-1β increased, and decomposition of gasdermin D accelerated." (PMID 35265087, 2022). "In this study, we systematically analyzed the serum levels of IL-1β, IL-2, IL-4, IL-6, IL-8, and IL-10 in COVID-19 patients with different disease severities, as well as in healthy controls." (PMID 35540724, 2022). "In this regard, detecting IL-1RA has been proposed as a systemic indicator of IL-1β production, and our study, in agreement with previous studies, shows an important increase in IL-1RA in the plasma of COVID-19 patients." (PMID 35663992, 2022). "We recently showed that platelets from critically ill COVID-19 patients induce IL-1β secretion in monocytes." (PMID 35842415, 2022). "Previous reports suggest that SARS-CoV-2 infection senses NRLP3 and that increased levels of IL-1β and IL-18 in plasma correlate with disease severity and mortality in patients with COVID-19." (PMID 36498845, 2022). "At present, a number of clinical studies have been carried out to down-regulate the levels of inflammatory factors in patients with COVID-19, including monoclonal antibodies against IL-6 and IL-1β, and inhibitors of JAK-STAT signaling pathway." (PMID 35935817, 2022).
COVID-19 (continued). "In stage III of COVID-19 patients, moderate positive correlation was noticed between Gal-1 and IL-1β (p = 0.001) and IL6 (p = 0.005) and strong positive correlation between Gal-1 and IL-10 (p = 0.001), IL-23 (p = 0.001) and IL-33 (p = 0.001)." (PMID 35075140, 2022). "The most important inflammatory mediators released by immune cells during the “cytokine storm” are IFN-α, IFN-γ, IL-1β, IL-6, IL-12, IL-18, IL-33, TNF-a, and TGF-β and they are associated with different clinical features of COVID-19." (PMID 36298472, 2022). "Inflammatory mediators IL-1β and IL-18, the main cytokine products of caspase-1 activation, are observed to be increased in the lungs and sera of patients with symptomatic COVID-19 compared to asymptomatic patients and healthy individuals." (PMID 35265086, 2022). "In support of a key role of IL-1β in patients with severe COVID-19 we and others have recently reported the potential efficacy of blocking IL-1β by using anti-IL1 drugs." (PMID 36096831, 2022). "The pathogenesis of COVID-19 encompasses a “cytokine storm” which includes pro-inflammatory interleukins (IL-1β, IL-6) and the tumor necrosis factor (TNF-α)." (PMID 35925914, 2022). "Immunohistochemical staining showed that endothelial cells expressed IL-1β in lung samples obtained from the COVID-19 group (p < 0.001)." (PMID 34463916, 2022). "This latter study confirms our reported data on IL-1β, showing an increased expression in COVID-19 patients." (PMID 36422642, 2022). "Analysis of postmortem tissue from people who died due to influenza, bacteria pneumonia, ARDS, and COVID-19 has recently shown that activated (IL-1β– and IL-6–producing) monocytes and macrophages are significantly more abundant in the COVID-19 lung." (PMID 34710339, 2022). "The main results are that the levels of inflammatory cytokines decreased considerably at 4–6 weeks compared to at the time of admission in the acute phase of COVID-19, except for IL-1β, which increased at 4–6 weeks after admission." (PMID 35330391, 2022). "We also observed the downregulation of IL-1β mRNA expression in COVID-19 patients, indicating a shift from pro-inflammatory to a regulatory phenotype in monocytes in COVID-19." (PMID 35064122, 2022). "Recent studies reported increased blood levels of IL-1β in COVID-19 patients compared to healthy subjects." (PMID 36422642, 2022). "Elevated IL-1β levels have been associated with SARS, hypercoagulation, disseminated intravascular coagulation, and most severe COVID-19 cases." (PMID 35464491, 2022). "Recently, Shi and others (2020b) found higher serum concentrations of MMP-3 in COVID-19 patients than in healthy individuals, and their levels correlated with inflammatory markers such as IL-6 and IL-1β." (PMID 35647937, 2022). "Serum concentrations (log2) of M65 were higher among patients with severe COVID-19 and positively correlated with serum IL-1β concentrations (Spearman’s r = 0.34, p = 0.0024)." (PMID 34997207, 2022). "IL-1β was doubled in COVID-19 patients compared to healthy subjects, with a positive trend due to severity, in lack of statistical significance." (PMID 35508575, 2022). "Together, we show that IFN-λ is negatively affected by viral infection, supporting the idea that IFN-λ administration together with the pharmaceutical blockage of IL-1β represents a promising approach to revert the COVID-19-induced cytokine storm." (PMID 36422642, 2022). "In the severe COVID-19 cases in this study, IL-1β significantly decreased and IL1Ra significantly increased as a part of the marked immune dysregulation." (PMID 35529862, 2022). "This is significant because TLR7/8 activation of NF-κB increases cytokine production and, in conjunction with inflammasome activity, NF-κB drives an axis of IL-1β, IL-6, IL-12, TNFα, and Th1 T-cell hyperinflammation as part of COVID-19 immunopathology." (PMID 35261923, 2022).
COVID-19 (continued). "They observed a “key COVID-19 feature” shared by the moderate and severe disease groups, which they defined as the following inflammatory cytokines: IL-1α, IL-1β, IL-17A, IL-12 p70, and IFNα." (PMID 35774397, 2022). "In patients recovering from mild COVID-19, there was a trend for higher IL-1β, IL-6, and TNF-α production." (PMID 35380990, 2022). "We have reported the application of a cytokine panel (serum, IL-1β, IL-6, IL-8 and TNFα) using the automated EllaTM platform and its potential clinical utility in the assessment of patients with COVID-19." (PMID 35500008, 2022). "Single-cell profiling of bronchoalveolar lavages from critically ill COVID-19 patients revealed the abundant presence of inflammatory IL-1β-secreting myeloid cells." (PMID 36209522, 2022). "We systematically searched records investigating the role of interleukins (IL-1β, IL-2, IL-4, IL-6, IL-8, and IL-10) in COVID-19 patients in Web of Science, Pubmed, and Embase through December 2020." (PMID 35540724, 2022). "Inflammasome activation and pyroptosis have been the focus of extensive research due to their connection with cytokine processing and release of IL-1β, which has been shown to play a critical role in the development of severe COVID-19." (PMID 35244141, 2022). "Increased cytokine production, especially IL-1β, IL-6, and IL-10, is another critical characteristic of severe COVID-19." (PMID 36226148, 2022). "Studies have shown that severe COVID-19 is accompanied by hypercytokinemia with high levels of pro-inflammatory cytokines such as IL-6 and IL-1β as well as anti-inflammatory cytokines such as IL-4 and IL-10." (PMID 35007290, 2022). "The tear film concentrations of VEGF and IL-10 were found to be significantly increased, whereas TNF-α, IL-1β, IL-8, and GM-CSF were significantly lower among the COVID-19 patients admitted to the hospital than among the SARS-CoV-2-negative controls." (PMID 35566776, 2022). "BALF-derived macrophages from patients with COVID-19 show especially high response scores for IL-1β and TNF in their pro-inflammatory subset." (PMID 35732153, 2022). "Our findings demonstrated that two groups of COVID-19 patients had significant increases in four pro-inflammatory cytokines (IL-1β, IL-6, and IL-18) and two anti-inflammatory cytokines (IL-4 and IL-35)." (PMID 36298501, 2022). "The literature suggests that IL-6 and IL-1β play a prominent role in the pathogenesis and severity of COVID-19, and that is why the IL-6 and IL1β antagonists are in a clinical trial." (PMID 36298704, 2022). "The results showed that the level of pro-inflammatory cytokines, TNF-α, IL-6, IL-8, and IL-1β were significantly elevated in severe COVID-19 patients, but the alarmin molecules IL-1α and HMGB1 were marginally higher." (PMID 36585712, 2022). "COVID-19 provokes an NLRP3-mediated increase in IL-1β expression, similar to the NLRP3-inflammasomopathies." (PMID 36034552, 2022). "Elevated serum levels of IL-6, IL-8, IL-1β, and TNF-α correlate with moderate and severe COVID-19, while IL-12p70 and IL-2 serum expression is associated with asymptomatic and mild diseases." (PMID 36526691, 2022). "We also measured saliva levels of TNFα and IL-1β, as known markers of inflammation and organ damage, and commonly reported to be elevated in blood of patients with COVID-19." (PMID 36136963, 2022). "In contrast, in the study by Kang and co-authors these cytokines, including IL-1β, IL-12p40, and IL-17 were undetectable in patients with severe COVID-19." (PMID 35213582, 2022). "Analyses of patients in stage II of COVID-19 revealed a moderate positive correlation between Gal-1 and IL-1β (p = 0.004) and strong positive correlations between Gal-1 and IL-23 (p = 0.001) and IL-33 (p = 0.001)." (PMID 35075140, 2022). "Infected monocytes secrete the pro-inflammatory cytokines interleukin-1β (IL-1β) and IL-18, which contribute to systemic inflammation and severe coronavirus disease 19 (COVID-19)." (PMID 35871170, 2022).
COVID-19 (continued). "In agreement with prior large-scale studies from patients and animal models of COVID-19, we found the hamster model of disease also has upregulated levels of IL-1β, CXCL5, and CXCL10." (PMID 36614003, 2022). "The spike protein produced by the COVID-19 mRNA vaccine or by SARS-CoV-2 itself induces IL-1β secretion in macrophages." (PMID 35746474, 2022). "Among these, changes in IL-6, IL-1β and TNF-α levels were the best documented in the hyperinflammatory response associated to COVID-19 and ARDS." (PMID 36466830, 2022). "In this review, we summarize current evidence supporting the involvement of the NLRP3 inflammasome and IL-1β in the pathogenesis of COVID-19." (PMID 36209522, 2022). "Researchers have found that the severity of COVID-19 is positively correlated with the levels of IL-1β and IL18 in plasma." (PMID 36389144, 2022). "In agreement with previous studies, we found that severe COVID-19 patients had elevated serum levels of IL-1α, IL-1β IL-6 and IL-18." (PMID 36142255, 2022). "In this meta-analysis, we analyzed serum levels of IL-1β, IL-2, IL-4, IL-6, IL-8, and IL-10 in COVID-19 patients with different disease severities." (PMID 35540724, 2022). "Accordingly, the IL-1β tear film concentration was found to be higher in patients with pneumonia complicating COVID-19 (median [IQR] = 0.52 [0.96] pg/ml for patients with pneumonia vs 0.28 [0.29] pg/ml for patients without pneumonia; p = 0.0041)." (PMID 35508669, 2022). "It is already known that cytokine storm (hypercytokinemia) resulting in increased systemic inflammation with high levels of IL-6, IL-1β, and TNFα is induced by viral infections, including influenza A and COVID-19." (PMID 36504633, 2022). "Of note, high levels of IL1B and IL6 have been linked to the worse prognosis in patients with COVID-19." (PMID 35705998, 2022). "Bacterial and endotoxin translocation in COVID-19 induces a significant increase in several markers of systemic inflammation, such as IL-6, IL-1b, IL-8, MCP-1, IP-10 and TNF-a." (PMID 35630492, 2022). "The systemic inflammation elicited by COVID-19, increases the levels of several inflammatory molecules, including C-reactive protein, IL-1β, IL-2, IL-6, IL-8, IL-10, and TNF-α." (PMID 36439786, 2022). "A massive pro-inflammatory profile mediated by IL-1β, IL-6, TNF and IFN-γ together with lower levels of IL-10 was a systemic hallmark of critically ill COVID-19 patients." (PMID 35720401, 2022). "Earlier studies had indicated that severely/critically ill COVID-19 cases had elevated serum levels of interleukins (IL-1β, IL-2, IL-4, IL-6, IL-10)." (PMID 36415655, 2022). "From this search, we identified 6 cytokines that are critically involved in the pathogenesis of COVID-19 induced ARDS lung injury (IL-1β, IL-2, IL-6, IL-8, IL-10, and TNFα)." (PMID 35033181, 2022). "The increased expression of IL-1 inhibitory receptor 2 (IL1R2) in MDSC monocytes is interesting considering the role of dysregulated monocyte responses and elevated levels of serum inflammatory cytokine, including IL-1β reported in severe COVID-19 patients." (PMID 36817759, 2022). "We evaluated IL-17A, TNFα, IL-1β protein levels in saliva of COVID-19 patients with different severities, and found that among these cytokines, IL-17A was associated with COVID-19 severity and poor patient survival outcomes." (PMID 36136963, 2022). "In this study, we identified that the serum levels of IL-6, IL-2R, IL-10, TNF-α, IL-1β, IL-4, IL-8 and IL-17 were significantly elevated in the severe or death cases and probably play crucial roles in the progression of COVID-19." (PMID 35237162, 2022). "Altogether, mucosal spike and NP-specific IgG and S1-specific IgA persisting after lung severe acute respiratory syndrome coronavirus 2 (SARS-CoV-2) clearance and low pulmonary IL-1β correlate with COVID-19 fatal outcome." (PMID 36248831, 2022).
COVID-19 (continued). "The percentage and counts of immune-suppressive monocytes (mo-MDSCs) identified as CD14+ HLA-DR− monocytes were higher than normal values in severe COVID-19+ patients, independently from the amount of IL-6, IL-1β, IL-17A, TGF-β, TNF-α and IFN-γ." (PMID 35508575, 2022). "Overexpression of cytokines (IFN-γ, IL-1β, IL-2, IL-4, IL-6, and IL-10) have been observed in COVID-19 patients." (PMID 35168674, 2022). "Recent evidence proposed that the severity of the coronavirus disease 2019 (COVID-19) in patients is a consequence of cytokine storm, characterized by increased IL-1β, IL-6, IL-18, TNF-α, and IFN-γ." (PMID 36111104, 2022). "Among these, we observed a significant decrease in the three best documented general pro-inflammatory markers in COVID-19: IL-6, IL-1β and TNF-α." (PMID 36466830, 2022). "A similarly increased IL-1β production was seen in the culture medium of TMNK-1 cells when exposed to COVID-19 exosomes." (PMID 35587188, 2022). "Increased IL-1α and IL-1β expression was revealed in severe COVID-19 patients prior to development of respiratory distress." (PMID 36422492, 2022). "Blocking the IL-1b/IL-1R interaction using anakinra (an IL-1R inhibitor) has shown promising results in initial clinical trials, reducing COVID-19 severity." (PMID 36187170, 2022). "Meanwhile, previous studies showed that patients with COVID-19 were in a pro-inflammatory status with high levels of IL-1β and other cytokines, and high levels of IL-6 and TNF-α were observed in COVID-19 patients requiring intensive-care-unit hospitalization." (PMID 34863291, 2021). "A recent randomized controlled trial study demonstrated that administration of curcumin in nano micelles form significantly decreases IL6 and IL-1β in COVID-19 patients." (PMID 34513735, 2021). "Among the antiviral activities that melatonin has, by suppressing multiple inflammatory pathways (e.g., IL6 and IL-1β), these effects are directly relevant given the well-described pulmonary pathophysiological characteristics of patients with severe COVID-19." (PMID 35723382, 2021). "This includes for example therapeutic antibodies interfering with either IL1β, IL6, TNFα or their receptors directly contributing to the CRS associated with severe COVID-19." (PMID 34293006, 2021). "Cytokine secretion for Nano-curcumin-treated COVID-19 patients was reduced in comparison to placebo group (Paired T-test, p = 0.0082 for IL-1β and p = 0.0038 for IL-6)." (PMID 34443474, 2021). "Cytokine profiles in COVID-19 patients have revealed increased levels of interleukin-1β (IL-1β), IL-2, IL-6 and tumor necrosis factor-alpha (TNFα)." (PMID 33927728, 2021). "In COVID-19 patients, a pro-inflammatory status with high levels of IL-1β, IL-6 and TNF-α have been demonstrated." (PMID 34313585, 2021). "The coronavirus tolerance observed in bats has been associated to a dampened transcriptional priming of NLRP3, which confirms that targeting the NLRP3/IL-1β pathway is a successful strategy in COVID-19." (PMID 33916409, 2021). "A significantly higher proportion of COVID-19 convalescent individuals presented with increased IL-5, IL-6, and IL-1β levels." (PMID 34234102, 2021). "Further, in patients with milder stage of COVID-19, positive correlation was detected between IL-33 and IL-1β (p = 0.024), IL-12 (p = 0.000), and IL-23 (p = 0.000), respectively." (PMID 34917631, 2021). "Female patients also exhibited reduced levels of IL-1β when compared with male patients, a proinflammatory cytokine considered a potential target for COVID-19 therapy." (PMID 34027897, 2021). "In 2020, IL-1β, IL-6, and other proteins were found to be correlated with pulmonary inflammation with extensive lung involvement, as seen in COVID-19 patients." (PMID 34017253, 2021). "For example, pro-inflammatory cytokines and chemokines CXCL8 (q < 2.0 × 10−16), IL18 (q = 0.009), and IL1B (q < 2.0 × 10−16) were elevated in monocytes from male patients with severe COVID-19 compared to females." (PMID 34330889, 2021).